LINC00261 (long independently transcribed non-coding RNA 261)
Diseases named in the same sentence as LINC00261 in open-access papers (continued):
Sharing a sentence is not in itself a finding about the gene and the disease.
cancer (28 papers, 2017 to 2025). A tumor composed of atypical neoplastic, often pleomorphic cells that invade other tissues. "Furthermore, we give insight into how LINC00261 can sponge multiple miRNAs to its target and regulate various cancer-associated signaling pathways." (PMID 40136629, 2025). "Thus, LINC00261 is a lncRNA associated with diverse forms of cancer, is highly conserved evolutionarily, and is co-regulated with its neighboring gene FOXA2 during EMT and tumorigenesis." (PMID 30597925, 2018). "The LINC00261 is found to be aberrantly expressed in various cancers such pancreatic, gastric, colorectal, lung, hepatocellular, breast, laryngeal, endometrial, esophageal, prostate, choriocarcinoma, thyroid, and bile duct cancers." (PMID 40136629, 2025). "Human lncRNA DEANR1/linc00261 is involved in many cellular processes, including ones crucial for cancer development." (PMID 35740417, 2022). "All of these studies on various cancers suggest both MiR105 and LINC00261 play important roles in cancer occurrence and progression." (PMID 35702258, 2022). "Studies of DEANR1/linc00261 were mainly conducted in the cancer cells, in which the overexpression of lncRNA inhibits cell proliferation and both cell invasion and migration by various ways." (PMID 35740417, 2022). "This positive transcriptional correlation was evident even in other cancers, and in normal tissues, both LINC00261 and FOXA2 were highly co‐expressed in endoderm‐derived organs." (PMID 33793068, 2021). "Mechanistically, the sponging and binding to miRNAs indicates that LINC00261 acts as a ceRNA to inhibit the expression of cancer-related genes." (PMID 34022894, 2021). "An increasing number of studies have indicated that LINC00261 plays vital roles in a variety of cancers." (PMID 34022894, 2021). "This overview of the many types of cancer related to LINC00261 expression expands the map of LINC00261 and influences further researches." (PMID 34022894, 2021). "We validated the expression of LINC00261 from lncRNA microarray data by comparing data from the public cancer databases GEO and TCGA and showed that LINC00261 is downregulated in PC, consistent with the results of previous studies 18-20." (PMID 32929371, 2020). "Many studies have proven that LINC00261 can inhibit cell proliferation and invasion, thus promoting the development of cancer." (PMID 31179185, 2019). "This review discusses how LINC00261 modulates oncogenic pathways in various cancers." (PMID 40136629, 2025). "Moreover, through the TCGA (The Cancer Genome Atlas) database, the authors found low expression of LINC00261 in PC patients compared to healthy individuals, which also correlates with poor patient survival." (PMID 40136629, 2025). "LINC00857 and LINC00261 are also related to cancer invasion and migration." (PMID 35571069, 2022). "The evidence that LINC00261 plays an antineoplastic role in a variety of human cancers indicates that it has the potential to be a target for both cancer diagnosis and treatment and could become a biomarker for many types of cancer." (PMID 34022894, 2021). "In addition to discussing LINC00261 expression and its clinicopathological features for the cancers above, the biological functions and molecular mechanisms of LINC00261 are summarized below." (PMID 34022894, 2021). "However, in present study, we found that LINC00261 was upregulated in the cancer tissues for aged 40–64 years BRCA patients." (PMID 33968126, 2021). "LINC00261 has been shown to exert as a molecular biomarker in several cancers." (PMID 31772674, 2019). "Additionally, we discovered that LINC00261 acts as a molecular sponge for miRNAs, such as miR-550a-3p, miR-23a-3p, miR-148a, miR-324-3p, and miR-105-5p, regulating critical cancer-related signaling pathways, including PI3K/Akt/mTOR, Protein kinase B, and Mammalian target of rapamycin (mTOR)." (PMID 40136629, 2025).
cancer (continued). "In addition, other studies suggested that LINC00261 might act as a sponge for several miRNAs, as it was found in several comprehensive analyses of ceRNA networks in different types of cancer." (PMID 32414223, 2020). "In this study, we investigated the influence of linc00261 on regulating EMT and cancer stem cell-liked characteristics in HCC, and the exact role of linc00261 in modulating SMAD3, the key factor of TGF-β1 signaling." (PMID 35123494, 2022). "Moreover, the localization or function of LINC00261 might also differ between normal and cancer cells or even between different cancer types, which also warrants further investigation to fully understand the regulation and biological role of LINC00261 in cancer." (PMID 32414223, 2020). "According to LINC00261 expression in cancer cells, we chose A549 and SPCA1 cancer cells for overexpression of LINC00261." (PMID 31772674, 2019). "Consistent with the expression analysis in the 53 human tissue samples, the expression of AC007405.6, LINC00261, and RP11-672A2.4 and their targets were correlated in these 16 cancer types." (PMID 29303984, 2018). "Summing up, LL35/linc00261 is involved in the regulation of cell proliferation and migration by different mechanisms both in cancer and non-cancerous cells, while most molecular mechanisms are still under investigation." (PMID 35740417, 2022). "Furthermore, downregulation of LINC00261 altered the epithelial identity of PDAC cells by decreasing CDH1 levels and inducing an EMT-related transcription program that enhanced cancer cell invasion and migration." (PMID 32414223, 2020). "LINC00261, TNFRSF11A, CASP1, ST6GALNAC1, and PIGR also play prognostic roles in cancer." (PMID 31689990, 2019). "Moreover, it was also found some cancer‐specific lncRNAs, such as LINC01140, LINC00261, ABHD11‐AS1, and TINCR,58, 59, 60, 61 served as important biomarkers in other different cancer types as well." (PMID 30318850, 2018).
adenocarcinoma (1 paper, 2021). A common cancer characterized by the presence of malignant glandular cells. "Taken together, these results show that LINC00261 is selectively upregulated in human NEPC relative to both hormone‐sensitive and hormone‐independent adenocarcinomas, where its expression is positively associated with classical neuroendocrine markers." (PMID 33793068, 2021).
LINC00261 also shares sentences with these, for which no sentence is quoted: esophageal squamous cell carcinoma (3 papers); cholangiocarcinoma (2); adenoma (1); bile duct cancer (1); bladder cancer (1); colorectal cancer (1); dysplasia (1); glioblastoma multiforme (1); glioma (1); neuroblastoma (1); neuroendocrine neoplasm (1); stomach cancer (1).